KDM5C (lysine demethylase 5C)
Diseases named in the same sentence as KDM5C in open-access papers (continued):
Sharing a sentence is not in itself a finding about the gene and the disease.
colon adenocarcinoma (1 paper, 2021). "Intriguingly, we also found the significantly higher expression level of these immune checkpoints in KDM5C altered colon adenocarcinoma and uterine corpus endometrial carcinoma." (PMID 33953726, 2021). "Moreover, KDM5C altered colon adenocarcinoma and uterine corpus endometrial carcinoma had dramatically higher level of antitumor T effector signature." (PMID 33953726, 2021).
congenital glaucoma (1 paper, 2025). "KDM5C is a cause of X-linked syndromic intellectual developmental disorder, but the missense variant c.1204G>A p.(Asp402Asn) has been identified in one patient with Peters anomaly and congenital glaucoma." (PMID 41011222, 2025).
Cornelia de Lange syndrome (1 paper, 2024). A rare syndrome characterized by low birth weight, delayed growth, intellectual disabillity, behavioral problems, and a distinctive facial appearance (thin, arched eyebrows, low set ears, small teeth, and small nose). "Remaining Cornelia de Lange syndrome, KMT2A, KDM5C and CHD7 signatures reached 70–100% sensitivity at best with unstable performances, suffering from heterogeneous methylation profiles among cases and rare discordant samples." (PMID 37872275, 2024).
diffuse large B-cell lymphoma (1 paper, 2019). "Whereas, in diffuse large B-cell lymphoma a decrease, rather than increase in H3K4 methylation, seems pathogenic, KDM5C-driven augmentation of H3K4 methylation may contribute to the pathogenesis of acute B-cell leukemia; this is an observation similar to ours in MCL." (PMID 31334109, 2019).
endometrial carcinoma (1 paper, 2021). A malignant tumor arising from the epithelium that lines the cavity of the uterine body. "In TCGA cohort, endometrial carcinoma had the highest levels of KDM5C alterations (9.6%, 56/586)." (PMID 33953726, 2021).
glioma (1 paper, 2022). A benign or malignant brain and spinal cord tumor that arises from glial cells (astrocytes, oligodendrocytes, ependymal cells). "In this regard, the discovery of potent histone demethylase inhibitors across the JMJ family abled to inhibit glioma cell proliferation, such as GSK-J1/J4, encourages the design of new small-molecule inhibitors with selective pharmacological intervention against KDM5C." (PMID 36142158, 2022).
Glucose intolerance (1 paper, 2024). Glucose intolerance (GI) can be defined as dysglycemia that comprises both prediabetes and diabetes. "When treated with statin, wild-type Kdm5c+/+ female mice developed glucose intolerance as we have seen throughout our studies with female mice, but female Kdm5c+/– mice were protected from statin-induced glucose intolerance (compare red and blue stippled bars)." (PMID 38956041, 2024).
hepatitis B (1 paper, 2023). "While no KDM5C-specific inhibitor exists, pan-KDM5 inhibitors (KDM5i) are available and have been used in clinical trials for the treatment of cancer and hepatitis B." (PMID 37018401, 2023).
invasive breast carcinoma (1 paper, 2020). A carcinoma that infiltrates the breast parenchyma. "Among these cancers, mutations of KDM5C are the most prevalent in invasive breast carcinoma." (PMID 33324444, 2020).
ischemic stroke (1 paper, 2025). A stroke disorder caused by obstruction of blood flow to the brain, due to thrombotic (local blood clot formation) or embolic (due to a blood clot or other material traveling from another site) event. "Therefore, we explored whether KDM5C, KDM6A, or EIF2S3 displayed age-dependent expression changes in males and females and whether such age-dependent expression changes could be altered by ischemic stroke." (PMID 40191607, 2025).
liver fibrosis (1 paper, 2024). "In summary, KDM5B and KDM5C demethylases prevent liver fibrosis resolution after alcohol cessation in part through suppression of LXR activity." (PMID 37943941, 2024).
lymphoma (1 paper, 2019). A malignant (clonal) proliferation of B- lymphocytes or T- lymphocytes which involves the lymph nodes, bone marrow and/or extranodal sites. "While the first two were identified late in the disease, in the 2013 primary and cultured cells, KDM5C mutation was seen through the entire lymphoma history, including the samples examined in 2005, 2007, 2009, and 2013." (PMID 31334109, 2019).
Macrocephaly (1 paper, 2016). Occipitofrontal (head) circumference greater than 97th centile compared to appropriate, age matched, sex-matched normal standards. "While we observed distinct clinical features in some individuals (e.g. macrocephaly and seizures in the carriers of variants in KDM5C and GLDC, respectively), features specific to SMS are present in a sufficient number of probands." (PMID 27799067, 2016).
metastatic prostate carcinoma (1 paper, 2022). A carcinoma that arises from the prostate gland and has spread to other anatomic sites. "Here, we show that the histone demethylase KDM5C is highly expressed in metastatic prostate cancer." (PMID 35454801, 2022).
multiple myeloma (1 paper, 2026). "However, the role of KDM5C in multiple myeloma (MM) progression and bortezomib (BTZ) resistance has remained elusive." (PMID 41872155, 2026).
neuroblastoma (1 paper, 2020). Neuroblastoma (NB) is the most common solid, extracranial childhood tumor. "In addition, deregulated genes upon PHF6 KO significantly overlapped with deregulated genes after Kdm5c KO and with deregulated genes after TCF4 dosage alterations in neuroblastoma cells but not in human blood after correction for multiple testing." (PMID 33149206, 2020).
Obesity (1 paper, 2023). Accumulation of substantial excess body fat. "Previous rodent studies have revealed that X-linked genes involved in lipid metabolism, such as Kdm5c and Eif2s3x, are critical for sex differences in obesity and metabolism." (PMID 37437033, 2023).
osteoporosis (1 paper, 2023). A condition of reduced bone mass, with decreased cortical thickness and a decrease in the number and size of the trabeculae of cancellous bone (but normal chemical composition), resulting in increased fracture incidence. "Overall, our findings highlight an epigenetic mechanism that controls osteoclastogenesis by governing the transcriptional programming of energy metabolism, positioning KDM5C as a potential target for the treatment of osteoporosis in females." (PMID 37018401, 2023). "Our study showed that pharmacological inhibition of KDM5C blocks osteoclastogenesis of both human and mouse monocytes, indicating that KDM5C is a viable therapeutic target for osteoporosis, particularly for females." (PMID 37018401, 2023). "Our report details a sex-dependent mechanism for bone homeostasis, connecting epigenetic regulation to osteoclast metabolism and positions KDM5C as a potential target for future treatment of osteoporosis in women." (PMID 37018401, 2023). "Thus, KDM5C represents a cell-intrinsic, sex-dependent epigenetic regulator of osteoclastogenesis and bone mass in females, and its inhibition provides a potential therapeutic strategy for preventing osteoporosis in females." (PMID 37018401, 2023).
pancreatitis (1 paper, 2023). Inflammation of the pancreas. "KDM5C was found higher expressed in female PDAC patients and a history of pancreatitis." (PMID 37880235, 2023).
parathyroid tumors (1 paper, 2023). "This is relevant in the setting of parathyroid tumors due to the X chromosome harboring loci for the FLNA and KDM5C genes." (PMID 36900197, 2023).
Renal cyst (1 paper, 2021). A fluid filled sac in the kidney. "Notably, Kdm5c-knockout mice kidney tissues exhibited elevated glycogen level, reduced lipid peroxidation and displayed a transformation of renal cysts into hyperplastic lesions, implying a cancer-protective benefit of ferroptosis." (PMID 34522206, 2021).
schwannoma (1 paper, 2024). A benign, usually encapsulated slow growing tumor composed of Schwann cells. "ITIH4, a secreted protein that was enriched in conditioned media from schwannoma cells surviving radiotherapy, displayed closed chromatin and RNA suppression following snARC-seq suppression of KDM5C with radiotherapy." (PMID 38216587, 2024).
Silver-Russell syndrome (1 paper, 2023). Silver-Russell syndrome is characterized by growth retardation with antenatal onset, characteristic facies and limb asymmetry. "Reminiscent of patients and mice with KDM5C mutations, microduplications of the region harboring Cdkn1c cause Silver-Russell Syndrome, characterized by growth retardation and short stature." (PMID 36831303, 2023).
Sotos syndrome (1 paper, 2017). Sotos syndrome is a rare multisystemic genetic disorder characterized by a typical facial appearance, overgrowth of the body in early life with macrocephaly, and mild to severe intellectual disability. "Other groups have also identified epi-signatures in patients with Sotos syndrome, and the X-linked intellectual disability caused by the KDM5C gene." (PMID 28293299, 2017).
thyroid cancer (1 paper, 2016). "By contrast, somatic mutations of TCF12, KDM5C, IGF2BP3 and MAP4K3 have not been reported in any types of thyroid cancers." (PMID 27626165, 2016).
thyroid tumor (1 paper, 2024). A benign or malignant neoplasm affecting the thyroid gland. "However, the intracellular localization of KDM5C was different in normal thyroid tissues and thyroid tumors." (PMID 38610938, 2024).
uterus cancers (1 paper, 2016). "At variant level, somatic mutations of KDM5C (p.L756I) have been identified in other cancers including lung and uterus cancers (the COSMIC database)." (PMID 27626165, 2016).
tumor (95 papers, 2011 to 2026). "Of 52 primary ccRCC tumours in males, 19 showed loss of the Y chromosome and of these, only 1 showed mutation of KDM5C whereas 2 tumours with an intact Y chromosome showed KDM5C mutation." (PMID 39955388, 2025). "It is possible that loss of KDM5C function alters gene expression in each individual tumour in combination with the constellation of genetic mutations and signalling pathway states that govern the overall transcriptional output in that tumour." (PMID 39955388, 2025). "This genetic relationship between KDM5C and KDM5D mutation is consistent with the human data that indicates that KDM5C mutant male ccRCC tumours display concomitant loss of KDM5D function through Y chromosome loss." (PMID 39955388, 2025). "Exosomal miR-33a suppresses putrescine biosynthesis by targeting AGMAT in cancer-associated fibroblasts (CAFs) from tumour core region, where putrescine inhibits the expression of demethylase KDM5C." (PMID 40903826, 2025). "KDM5C is reported to be a histone H3K4-specific demethylase that is associated with tumor progression and poor prognosis." (PMID 39984452, 2025). "Further consistent with this idea, the up- and down-regulation of these genes were reversed by the co-mutation of KDM5C, which restores tumour formation by KDM5D mutant cells." (PMID 39955388, 2025). "The KDM5C gene is mutated in approximately 20% of ccRCC metastases but the molecular mechanisms through which loss of KDM5C function contribute to tumour evolution and metastatic spread remain incompletely characterised." (PMID 39955388, 2025). "Mutation of KDM5D in male 786-O cells prevented xenograft tumour formation and this phenotype was unexpectedly rescued by co-mutation of KDM5C, consistent with the co-occurrence of KDM5C mutation and loss of the Y chromosome in ccRCC." (PMID 39955388, 2025). "Mutations or dysregulation of the KDM5C gene have been closely correlated with tumor growth and progression." (PMID 38216914, 2024). "Loss of nuclear KDM5C was associated with increased KDM5C expression in the cytoplasm of tumor cells." (PMID 38610938, 2024). "Upregulation of TRIM11 enhances the growth and migration abilities of MDA-MB-231 cells, and also promotes tumor growth in vivo, while KDM5C activity inhibits tumor progression and rescues the phenotype caused by TRIM11." (PMID 38769556, 2024). "Mutations in KDM5C have recently been associated with increased tumor angiogenesis and longer progression-free survival on sunitinib." (PMID 38791934, 2024). "Targeting YY1 in KDM5C-deficient tumor cells effectively suppressed cell proliferation and tumorigenesis." (PMID 39433896, 2024). "Supporting a tumor suppressive function, KDM5C mutations have recently been reported in human hematological neoplasms, including AML." (PMID 36631623, 2023). "Given the role of the KDM5C protein as an oxygen sensor, we further analyzed the expression levels of hypoxic markers aiming to identify the tumor signatures associated with the changes in KDM5C." (PMID 36142158, 2022). "In summary, the present study firstly provides the evidence that KDM5C alterations were associated with enhanced tumor immunogenicity and inflamed anti-tumor immunity, which result in prolonged OS in cancer patients treated with ICIs." (PMID 33953726, 2021). "The metabolic changes caused by KDM5C deficiency altered the response of tumor cells to ROS and ferroptosis inducers, thereby enhancing the tumorigenicity." (PMID 34522206, 2021). "Overexpressing ZMYND8 transcriptionally represses the expression of drug resistance, stemness, and tumor-promoting genes by repressing their poised promoters in association with KDM5C and EZH2." (PMID 33323928, 2020). "The extent of this tumor suppressive activity has been expanded by a recent study showing that KDM5C deficiency results in genomic rearrangements and instability, leading to aggressive forms of ccRCC." (PMID 28812986, 2017).
tumor (continued). "We and others have reported the associations of PBRM1, SETD2, BAP1, and KDM5C mutations with advanced stage, grade, and tumor invasiveness, and discovered that SETD2 and BAP1 mutations are associated with lower cancer-specific survival rates." (PMID 25124064, 2014). "Based on our cohort (n = 14), we estimate that among patients harboring a mutation in PBRM1, SETD2, BAP1, or KDM5C, the mutation would be present in 75%, 70%, 58%, and 55% of the tumor, respectively." (PMID 25124064, 2014). "This was also observed at the transcriptional level where KDM5D mutation increased the expression levels of a series of putative tumour suppressor genes and decreased the expression of putative pro-proliferative genes, while KDM5C co-mutation reversed these transcriptional changes." (PMID 39955388, 2025). "Interestingly, in RCC tumours, 67% of KDM5C mutations are truncating, suggestive of a strong selective pressure to completely inactivate KDM5C function in this tumour type." (PMID 39955388, 2025). "Our own unpublished exome sequencing of metastatic ccRCC samples from 9 male patients revealed that 6 tumours exhibited loss of the Y chromosome, 2 of these tumours harboured KDM5C mutations and 1 additional tumour with an intact Y chromosome showed a KDM5C mutation." (PMID 39955388, 2025). "While these putative substrates remain to be validated and functionally characterised, it is plausible that some of these proteins may also be relevant to ccRCC biology in KDM5C mutant and/or Y-chromosome loss tumours." (PMID 39955388, 2025). "KDM5B, however, has been identified as a tumor suppressor in MLLr AML and NUP98r AML, and KDM5C has also recently identified as a tumor suppressor, with a particularly strong association between KDM5C expression and long-term progression-free survival in female patients with AML." (PMID 39403928, 2024). "Notably, tumor growth was markedly inhibited when both of KDM5C and YY1 were depleted, whereas the loss of either KDM5C or YY1 only negligibly influenced ACHN cell growth." (PMID 39433896, 2024). "The degree of YY1 chromatin recruitment was decreased in KDM5C-deficient tumor cells, and further inhibition of YY1 expression might completely suppress YY1-directed transcription and significantly impair the proliferation of tumor cells." (PMID 39433896, 2024). "Moreover, the overrepresentation of KDM5C mutations in female patients additionally supports KDM5C as a female-biased tumor suppressor." (PMID 36631623, 2023). "Indeed, KDM5C knockdown was found to increase the tumor size of VHL-deficient RCC cells in a xenograft model." (PMID 35805040, 2022). "Indeed, KDM5C overexpression is associated with increased tumor cell proliferation and tumorigenic progression in multiple cancer types, including colorectal, breast, ovary, and prostate." (PMID 36142158, 2022). "TCGA predicted JARID1C/KDM5C as a tumor suppressor, mutations in which drive cancer progression." (PMID 31221981, 2019). "Thus, based on the binomial calculation, in order to detect a mutation in PBRM1, SETD2, BAP1, and/or KDM5C with 90% certainty, a tumor would need to be genetically profiled in at least three locations." (PMID 25124064, 2014). "In addition to analyses of human ccRCC tumours segregated based on Y chromosome and KDM5C mutation status, functional experiments introducing Kdm5c and Kdm5d mutations into mouse autochthonous ccRCC models could be informative." (PMID 39955388, 2025).